BRAP (BRCA1 associated protein)
Description:
Negatively regulates MAP kinase activation by limiting the formation of Raf/MEK complexes probably by inactivation of the KSR1 scaffold protein. Also acts as a Ras responsive E3 ubiquitin ligase that, on activation of Ras, is modified by auto-polyubiquitination resulting in the release of inhibition of Raf/MEK complex formation. May also act as a cytoplasmic retention protein with a role in regulating nuclear transport.
Synonyms: IMP; RNF52; BRAP2
Tractability: PROTAC: ubiquitination databases record sites on it; its protein half-life has been measured.
Target class: Enzyme; Transferase
Gene: Protein-coding gene on chromosome 12 (111,642,146 to 111,685,991, reverse strand). Ensembl gene ENSG00000089234.
Subcellular location: Cytoplasm
Subcellular location (Human Protein Atlas): Cytosol; Nuclear membrane
Pathways (Reactome):
Disease: Paradoxical activation of RAF signaling by kinase inactive BRAF; Signaling by moderate kinase activity BRAF mutants; Signaling downstream of RAS mutants
Signal Transduction: Negative regulation of MAPK pathway; RAF activation
Gene Ontology:
Molecular function: identical protein binding; protein binding; protein sequestering activity; ubiquitin protein ligase activity; ubiquitin-protein transferase activity; nucleic acid binding; zinc ion binding
Biological process: MAPK cascade; negative regulation of signal transduction; protein ubiquitination; Ras protein signal transduction
Cellular component: cytoplasm; cytosol; ubiquitin ligase complex
Genetic constraint (gnomAD): Loss-of-function variants: 33 observed, 57.63 expected, observed/expected ratio (o/e) 0.57, 90% interval 0.43 to 0.77. The upper end of that interval is the gene's LOEUF score, 0.77, which puts it in group 3 of 6, group 1 being the genes least tolerant of losing a copy. Missense variants: 542 observed, 690.48 expected, observed/expected ratio (o/e) 0.78, 90% interval 0.73 to 0.84. Synonymous variants: 230 observed, 242.32 expected, observed/expected ratio (o/e) 0.95, 90% interval 0.85 to 1.06.
Homologues: Orthologues: chimpanzee BRAP (99% identical), macaque BRAP (99% identical), dog BRAP (97% identical), guinea pig BRAP (94% identical), rabbit BRAP (94% identical), pig BRAP (91% identical), mouse Brap (91% identical), rat Brap (91% identical), tropical clawed frog brap (82% identical), zebrafish brap (77% identical), Drosophila melanogaster CG5555 (39% identical), Caenorhabditis elegans brap-2 (38% identical).
Diseases named in the same sentence as BRAP in open-access papers:
BRAP is named in the same sentence as 48 diseases in open-access papers, as found by Europe PMC text mining. Sharing a sentence is not in itself a finding about the gene and the disease. The quoted sentences say what the papers report.
metabolic syndrome (7 papers, 2011 to 2026). A cluster of metabolic risk factors for CARDIOVASCULAR DISEASES and TYPE 2 DIABETES MELLITUS. "BRAP is a protein-coding gene, and diseases associated with BRAP include myocardial infarction, cardiovascular diseases, and metabolic syndrome." (PMID 41554047, 2026). "In addtion, several studies revealed that BRAP is genetic risk factor for coronary artery disease including myocardial infarction, hypertension, metabolic syndrome." (PMID 30703135, 2019). "Only one report showed that a BRAP polymorphism was associated with metabolic syndrome in European American and African American populations." (PMID 23356535, 2013). "BRAP rs3782886 was associated with the risk of metabolic syndrome in a young adult Chinese population, the risk of alcohol dependence and scores on the alcohol use disorders identification test, and activation of endothelial repair activity in elderly Japanese individuals." (PMID 38448893, 2024).
myocardial infarction (6 papers, 2019 to 2026). Gross necrosis of the myocardium, as a result of interruption of the blood supply to the area, as in coronary thrombosis. "First, BRAP is associated with a risk of myocardial infarction and a phenotype of metabolic traits in Asian populations." (PMID 33093602, 2020). "Rs3782886 in the BRAP gene (breast cancer suppressor protein (BRCA1)-associated protein) has been associated with many traits in East Asians, include alcohol-related traits, myocardial infarction, and a biochemical trait—alanine aminotransferase level." (PMID 35094024, 2022).
Hypertension (4 papers, 2019 to 2025). The presence of chronic increased pressure in the systemic arterial system. "In a study of elderly Japanese population that accounted for smoking status, the minor allele of rs3782886 at BRAP was inversely associated with hypertension only in participants with high hematopoietic activity." (PMID 41480028, 2025). "A minor allele of BRAP-related SNP (rs3782886) has been found to be positively associated with platelet count and inversely associated with hypertension." (PMID 33514303, 2021). "The minor allele of single nucleotide polymorphism (SNP) in breast cancer suppressor BRCA1-associated protein (BRAP), which has a common etiology with HTLV-1 infection, has been reported to be positively associated with carotid atherosclerosis, but inversely associated with hypertension." (PMID 33514303, 2021). "Single nucleotide polymorphisms (SNPs) in breast cancer suppressor BRCA1-associated protein (BRAP) activate an inflammatory cascade via the activation of the NF-κB pathway and increase the risk of carotid atherosclerosis, while reducing the risk of hypertension." (PMID 33514303, 2021).
atherosclerosis (3 papers, 2013 to 2026). A disease characterized by the build-up of fatty material and calcium deposition in the arterial wall resulting in partial or complete occlusion of the arterial lumen. "BRCA-1 associated protein (BRAP), a newly identified risk gene for MI, aggravates the inflammatory response in atherosclerosis." (PMID 23356535, 2013). "SNP rs3782886 is known to be located on the BRAP gene on chromosome 12q24, and higher expression of BRAP with the minor allele (G allele) is associated with increased risk of atherosclerosis through enhancing the degree of inflammation via activation of NF-κB protein." (PMID 29165153, 2017). "Because atherosclerosis can be caused by a chronic inflammatory condition, BRAP might play a role in the occurrence of ischemic stroke." (PMID 23356535, 2013). "Five of them (ANGPTL4, APOB, BRAP, LPA, and ZPR1), were associated with increased levels of arteriosclerosis/atherosclerosis and risk of CVD, whereas four (DUSP13, FN1, IL6R, and MMP12) were associated with reduced levels of arteriosclerosis/atherosclerosis and risk of CVD." (PMID 42133815, 2026).
colorectal cancer (2 papers, 2019 to 2020). A primary or metastatic malignant neoplasm that affects the colon or rectum. "Recently, BRAP has attracted attention because its expression is associated with the prognosis of patients with colorectal cancer and the invasiveness of esophageal squamous cell carcinoma." (PMID 30703135, 2019). "In addition, genetic polymorphisms in BRAP locus are associated with a risk of colorectal cancer." (PMID 33240929, 2020).
esophageal squamous cell carcinoma (2 papers, 2019 to 2020). Esophageal squamous cell carcinoma (ESCC) is a type of esophageal carcinoma (EC) that can affect any part of the esophagus, but is usually located in the upper or middle third. "In our previous two studies, we found that BRAP was an esophageal squamous cell carcinoma (ESCC) susceptible gene and played an important role in ESCC invasion and metastasis." (PMID 33240929, 2020). "BRCA1-associated protein (BRAP) is a critical gene that regulates inflammation-related signaling pathway and affects patients’ prognosis in esophageal squamous cell carcinoma (ESCC)." (PMID 33240929, 2020).
Obesity (2 papers, 2020 to 2021). Accumulation of substantial excess body fat. "For instance, SNPs in BRAP (BRCA1 associated protein) were shown to associate with obesity and other metabolic abnormalities." (PMID 34107880, 2021). "Another hub, BRAP, has a polymorphism associated with obesity and other metabolic traits, which can play a role in effecting insulin signaling and aging." (PMID 32205467, 2020). "For instance, a significant positive association between log (root−to−tip ω) and log (body mass) was tested in BRAP, STX16, ZGRF1 and ZPLD1, and all four genes were reported to cause obesity in humans." (PMID 34107880, 2021).
Stroke (2 papers, 2013 to 2026). Sudden impairment of blood flow to a part of the brain due to occlusion or rupture of an artery to the brain. "The aim of this study was to test the association between the BRAP gene and stroke in a Taiwanese population." (PMID 23356535, 2013). "The aim of the present study was to investigate whether BRAP confers a risk for stroke in a Taiwanese population." (PMID 23356535, 2013). "Therefore, we concluded that SNP rs11066001 in the BRAP gene was unlikely to play an important role in stroke susceptibility in the Chinese population." (PMID 23356535, 2013). "However, further large-scale studies to explore the role of BRAP in stroke subtypes are needed." (PMID 23356535, 2013). "Of these, 5 proteins (ACOX1, BRAP, ERP29, FGF5, and FURIN) also showed strong colocalization with CAD and/or stroke and all had concordant direction of effects for BP and CAD and/or stroke." (PMID 41065563, 2026). "Therefore, we propose that age is unlikely to modify the relationship between BRAP gene and stroke." (PMID 23356535, 2013). "Therefore, whether or not BRAP SNP rs11066001 can influence a particular type of stroke needs further investigation." (PMID 23356535, 2013).
uveal melanoma (2 papers, 2019 to 2023). A melanoma derived from melanocytes of the uveal tract. "They differ, for instance, in the oncogenic driver mutations, mainly alterations in MAPK signaling in cutaneous melanoma and alterations in GNAQ/GNA11 signaling or the BRCA1-associated protein BAP1 in uveal melanomas." (PMID 37577930, 2023). "Uveal melanoma (UM) remains without effective therapy at the metastatic stage, which is associated with BAP-1 (BRCA1 associated protein) mutations." (PMID 31146482, 2019).
alcohol use disorder (1 paper, 2024). "Sixteen samples (20%) were analyzed for BRAP rs3782886, which has been shown to contribute to a predisposition for an alcohol use disorder." (PMID 38448893, 2024).
autoimmune disease (1 paper, 2021). A disorder resulting from loss of function or tissue destruction of an organ or multiple organs, arising from humoral or cellular immune responses of the individual to their own tissue constituents. "Our results also align with a large GWAS of 1 million participants of European ancestry which found that the lead variant at the BRAP gene (rs11065979) was positively associated with cardiometabolic and autoimmune diseases in overall and sex‐specific analyses." (PMID 33079445, 2021).
central obesity (1 paper, 2011). "The second new locus was rs11065987 (P = 2.9×10−10), located approximately 9.9 kb upstream of BRAP and associated with atherogenic dyslipidemia (3.1×10−3), vascular dysfunction (2.2×10−4), and central obesity (9.7×10−3)." (PMID 22022282, 2011).
chronic myeloid leukemia (1 paper, 2025). "For example, myeloproliferative diseases (excluding chronic myeloid leukemia, CML) have the most colocalized genes, including RPN1, BRAP, PPP1CC, ERP29, and PARP1." (PMID 41048997, 2025).
cognitive decline (1 paper, 2022). "Mapping of GWAS results identified genes that have been previously associated with cognitive decline including STAU1, SEMF3A, IP6K1, MST1, the ATNX2/BRAP locus, ALDH2 and DDX27, where a likely functional missense variant is highly associated." (PMID 35052462, 2022).
colon adenocarcinoma (1 paper, 2020). "Moreover, a positive relationship was found between BRAP expression and immune infiltrating cells including B cell, CD4 + T cell, CD8 + T cell, dendritic cell, macrophage cell, and neutrophil cell in colon adenocarcinoma (COAD), kidney renal clear cell carcinoma (KIRC), and LIHC." (PMID 33240929, 2020).
colon cancer (1 paper, 2021). "It was found that DNASE1L3, ITGA5, BRAP, and NFE2L2 were related to the immune infiltration of colon cancer." (PMID 35252219, 2021).
coronary atherosclerosis (1 paper, 2023). Atherosclerosis of the coronary vasculature. "Moreover, a polymorphism in the LGALS2 gene has been related to the severity of coronary atherosclerosis, but contrary to BRAP, not with MI." (PMID 37892153, 2023).
dementia (1 paper, 2025). Loss of intellectual abilities interfering with an individual's social and occupational functions. "Of them, a colocalized signal (that is, shared single causal variant, PP.H4 > 80%) was detected within APOE and BRAP genes for HFRS, whereas no colocalized signal with pQTL was detected within genes for HFRS without dementia." (PMID 40764432, 2025).
endometrial cancer (1 paper, 2019). Primary or metastatic malignant neoplasm involving the endometrium (mucous membrane that lines the endometrial cavity). "Six HiChIP target genes (BRAP, RASGRP1, HOXB1, HOXB6, HOXB7 and HOXB8) were enriched for miRNA targets of MIR196A1, itself a HiChIP target gene, providing evidence to link these genes together in a potential network that may mediate the effects of endometrial cancer risk variation." (PMID 31561579, 2019).
gastric cancer (1 paper, 2025). A primary or metastatic malignant neoplasm involving the stomach. "The results showed that knockdown of BRAP reduced the proliferation and migration of gastric cancer cells and inhibited the epithelial-mesenchymal transition (EMT) process." (PMID 40138287, 2025). "Overexpression of BRAP induced the proliferation, migration and EMT process of gastric cancer cells." (PMID 40138287, 2025).
hyperuricemia (1 paper, 2018). An abnormally high level of uric acid. "Of these SNVs, nine are located at seven gene loci (DDX39B, NFKBIL1, CDC42BPG, CDC63, BRAP, ACAD10, and PCNX3) that might be novel susceptibility loci for hyperuricemia." (PMID 29124443, 2018).
ischemic stroke (1 paper, 2013). A stroke disorder caused by obstruction of blood flow to the brain, due to thrombotic (local blood clot formation) or embolic (due to a blood clot or other material traveling from another site) event. "In the present study, we investigated the possible association between the genotypes of BRAP SNP rs11066001 and ischemic stroke in a Taiwanese population." (PMID 23356535, 2013). "The BRAP polymorphism may not play an important role in ischemic stroke in the studied population." (PMID 23356535, 2013).
mesothelioma (1 paper, 2021). A usually malignant and aggressive neoplasm of the mesothelium which is often associated with exposure to asbestos. "It has been recently reported that mesothelioma cells that lack BAP1 (BRCA1 Associated Protein) are sensitive to inhibition of the EZH2 (Enhancer of Zeste Homolog 2) histone methyltransferase." (PMID 34277422, 2021).
mild cognitive impairment (1 paper, 2020). "The AD module associated with regulation of lipolysis in adipocytes and neuroactive ligand-receptor interaction was not preserved in healthy and mild cognitive impairment networks and the key hubs TRPC5 and BRAP identified as potential targets for therapeutic treatments of AD." (PMID 32205467, 2020).
myeloproliferative diseases (1 paper, 2025). "Moreover, myeloproliferative diseases (excluding CML) and essential (haemorrhagic) thrombocythaemia have three identical colocalized genes, namely BRAP, PPP1CC, and ERP29." (PMID 41048997, 2025).
neurofibroma (1 paper, 2022). An intraneural or extraneural neoplasm arising from nerve tissues and neural sheaths. "Our findings indicate that tumor progression induced by SHP-2 (G503V) and its suppression by BRAP (G370A) may provide the basis for the development of new strategies for the treatment of NF1-MPNST as well as for the prevention of the malignant transformation of neurofibroma in individuals with NF1." (PMID 35625983, 2022).
rheumatoid arthritis (1 paper, 2016). A chronic, systemic autoimmune disorder characterized by inflammation in the synovial membranes and articular surfaces. "Other loci containing alleles robustly associated with higher eosinophil count and increased risk of rheumatoid arthritis were COG6, SPRED2, RUNX1, and the highly pleiotropic ATXN2/SH2B3/BRAP region." (PMID 27863252, 2016).
Tetralogy of Fallot (1 paper, 2013). A congenital cardiac malformation comprising pulmonary stenosis, overriding aorta, ventricular septum defect, and right ventricular hypertrophy. "The rs11065987 near the BRAP and ATXN2 gene was associated with both LDL and TC and has been reported to be a risk SNP of Tetralogy of Fallot." (PMID 27896059, 2013).
tumor (5 papers, 2017 to 2024). "Research has demonstrated that BRCA1-associated protein (BRAP) is a crucial protein involved in promoting tumour progression through its role in tumour immunity." (PMID 38722372, 2024). "Here, we applied genomic DNA sequencing to NF1-derived tumors and identified additional genetic alterations in PTPN11 (encoding Src homology region 2 domain-containing phosphatase-2 (SHP)-2) and BRAP associated with NF1 tumor malignancy." (PMID 35625983, 2022). "Genomic DNA sequencing allowed us to identify additional genetic alterations including mutations in the PTPN11 (encoding SHP-2) and BRAP genes that were associated with enhanced NF1-related tumor malignancy." (PMID 35625983, 2022). "However, the underlying mechanism of BRAP in tumor immunology is still unclear." (PMID 33240929, 2020). "BRAP was originally identified in a yeast two-hybrid screen for proteins interacting with the BRCA1 tumor suppressor." (PMID 35476518, 2022). "Further, we downloaded the data of tumor cell lines from the CCLE database and analyzed BRAP expression in 21 tumor cells." (PMID 33240929, 2020). "Results revealed that an increased BRAP expression correlated with poor prognosis in several tumor types, especially in LIHC." (PMID 33240929, 2020). "Moreover, we explored the correlation of BRAP expression with 6 tumor-infiltrating immune cells and immune checkpoint in 33 tumor microenvironments." (PMID 33240929, 2020). "Moreover, the correlation between BRAP expression and immune checkpoint marker implicates the role of BRAP in regulating tumor immunology in LIHC." (PMID 33240929, 2020). "Moreover, the correlation between BRAP and tumor immune infiltration was analyzed via the Tumor Immune Evaluation Resource (TIMER) database." (PMID 33240929, 2020). "We found that BRAP was expressed in all 21 kinds of tumor cells." (PMID 33240929, 2020). "Therefore, BRAP may play an important role in tumor immunity and be a potential prognosis biomarker in patients with LIHC." (PMID 33240929, 2020). "Tumor promotion by SHP-2 (G503V) and its suppression by BRAP (G370A) may serve as a basis for the development of new treatment strategies for NF1." (PMID 35625983, 2022). "We identified missense mutations of BRAP (c.1109G > C, p.Gly370Ala) and PTPN11 (c.1508G > T, p.Gly503Val) in the tumor-derived subclones but not in the parental sNF96.2-GFP cells." (PMID 35625983, 2022). "However, BRAP has not been shown to act as a tumor suppressor, and its physiological role is incompletely understood." (PMID 35476518, 2022).